LINC00434 (long independently transcribed non-coding RNA 434)
Gene: Long non-coding RNA gene on chromosome 13 (60,205,296 to 60,268,106, reverse strand). Ensembl gene ENSG00000227336.
Diseases named in the same sentence as LINC00434 in open-access papers:
LINC00434 is named in the same sentence as 1 disease in open-access papers, as found by Europe PMC text mining. Sharing a sentence is not in itself a finding about the gene and the disease.
LINC00434 shares sentences with these, for which no sentence is quoted: cancer (1 paper).